U3 (Small nucleolar RNA U3 )
Synonyms: LOC124904151
Gene: Small nucleolar RNA gene on chromosome 17 (48,382,371 to 48,382,586, reverse strand). Ensembl gene ENSG00000200538.
Gene Ontology:
Biological process: RNA processing
Cellular component: nucleolus
Homologues: Orthologues: chimpanzee U3 (99% identical), macaque U3 (96% identical), rabbit U3 (65% identical), rat LOC120102769 (65% identical). Paralogues in human: U3 (86% identical), SNORD3P1 (84% identical), SNORD3G (83% identical), SNORD3H (81% identical), U3 (81% identical), U3 (80% identical), SNORD3D (80% identical), SNORD3E (80% identical), U3 (79% identical), U3 (78% identical), U3 (77% identical), U3 (76% identical), and 10 more.